GSTM1 (glutathione S-transferase mu 1)
Diseases named in the same sentence as GSTM1 in open-access papers (continued):
Sharing a sentence is not in itself a finding about the gene and the disease.
colorectal cancer (continued). "In summary, the meta-analyses implied that the GSTM1 null variant was significantly associated with the susceptibility to colorectal cancer in Asians, which supporting the genetic factors play vital roles in the pathogenesis of colorectal cancer." (PMID 26219826, 2015). "The cumulative meta-analysis further showed a trend of an obvious association between the GSTM1 null genotype and colorectal cancer risk in Asians as information accumulated by year, moreover, the cumulative analysis accumulated by the sample size also supported the result." (PMID 26219826, 2015). "However, the previous studies which aimed to investigate the association of GSTM1 polymorphism and the colorectal cancer susceptibility in Chinese populations were controversial, and so were the genetic results in Asians." (PMID 26219826, 2015). "Overall, the pooled meta-analysis of eligible case-control studies suggested that GSTM1 null genotype was significantly associated with the risk to colorectal cancer in Asian populations (Z = 3.32, P = 0.001, OR = 1.05, 95% CI: 1.02–1.07) in a fixed-effect model." (PMID 26219826, 2015). "Therefore, we preformed the current meta-analysis to further explore whether the GSTM1 null polymorphism associated with the susceptibility to colorectal cancer." (PMID 26219826, 2015). "This genotype-dependent efficacy is robustly supported by epidemiological and clinical evidence in colorectal cancer, particularly for individuals with combined GSTM1 and GSTT1 null genotypes." (PMID 41246347, 2025). "In this follow-up research, we observed the interaction of these gene polymorphisms (COMT, GSTM1, GSTT1, MGMT, NQO1, and XRCC1) with different meat diets and on outcomes linked to colorectal cancer risk: ATNC levels, DNA adduct levels, and DNA strand breaks." (PMID 38337709, 2024). "Cox regression analysis confirmed the significance of both GSTM1-null and GSTP1 IleVal+ValVal (variant) genotypes as independent prognostic factors for increased overall mortality in patients with colorectal cancer." (PMID 38674199, 2024). "The combination of three GST genotypes, i.e., GSTM1 null, GSTT1 null, and GSTP1 Ile/Val or Val/Val genotypes, also demonstrated gene–gene interaction and further contributed to the increased risk of colorectal cancer." (PMID 39595582, 2024). "All these results justify the researchers’ focus on investigating the differential roles of GSTM1 in colorectal cancer." (PMID 38674199, 2024). "Previous studies described the associations between GST mutants (GSTM1 null and GSTT1 null) and location of colorectal cancers in individuals with mutation 1 in the MLH1 mismatch repair gene in Finnish kindreds." (PMID 34307686, 2021). "Results on GSTM1 and GSTT1 polymorphisms in relation to colorectal cancer are inconsistent as reviewed elsewhere." (PMID 20534171, 2010). "The GSTM1 and GSTT1 polymorphisms were unrelated to colorectal cancer risk singly or in combination in the present study." (PMID 20534171, 2010). "Our objective was to measure the interactions between common polymorphisms of P450 (CYP1A2, CYP1B1, CYP2E1), GSTM1 and T1, SULT1A1 and cigarette smoking in colorectal cancer (CRC)." (PMID 17603900, 2007). "The obtained results resemble the results from the analysis using previous models, further highlighting the role of GSTM1 and GSTP1 polymorphisms as possible determinants of mortality risk in patients with colorectal cancer (HR 1.89, p = 0.001 and HR 1.50, p = 0.046, respectively)." (PMID 38674199, 2024). "Their findings suggest that GSTM1 and GSTT1 polymorphism and its combination with GSTP1 may be associated with colorectal cancer (CRC) susceptibility in the Naswar-addicted Pashtun population of Pakistan." (PMID 39595582, 2024). "The mechanisms of GSTM1 gene methylation may provide interesting insights into the onset of colorectal cancer." (PMID 30578123, 2019).
colorectal cancer (continued). "GSTM1 null genotype was associated with a small, statistically significant increase in the risk of colorectal cancer in some case-control studies, but not in several other studies." (PMID 20534171, 2010). "Most of the previous studies found no increase in the risk of colorectal cancer in individuals with the combined null genotype of GSTM1 and GSTT1." (PMID 20534171, 2010). "But whether the GSTM1 polymorphisms confer the susceptibility to colorectal cancer in Asians has not been well established." (PMID 26219826, 2015). "In addition the study supports the notion that the biotransformation enzymes GSTM1, GSTP1 and EPHX1 may modify the effect of dietary factors on the risk of developing colorectal carcinoma and adenoma." (PMID 18093316, 2007). "This underscores that GSTM1 and GSTT1 genotypes are key determinants for stratifying individuals who would derive maximum benefit from SFN-based chemoprevention for colorectal cancer, with age and smoking history providing critical contextual refinement." (PMID 41246347, 2025). "This study assessed potential relationships between GSTM1, GSTT1, and GSTP1 polymorphisms and colorectal cancer (CRC) risk in Polish nonsmokers." (PMID 29765533, 2018). "Cytosolic GSTM1-1 and GSTT1-1 are especially significant in the biotransformation of polycyclic aromatic hydrocarbons, which can be detected in processed meat and cigarette smoke, which are well-recognized contributing factors to the development of colorectal cancer." (PMID 39125992, 2024).
gastric cancer (28 papers, 2007 to 2026). A primary or metastatic malignant neoplasm involving the stomach. "The GSTM1 null genotype was associated with a significantly increased risk of gastric cancer (adjusted OR 2.26, 95% CI 1.49-3.43; p < 0.001)." (PMID 42091970, 2026). "Third, inherited mutations of certain genes such as glutathione S-transferase mu 1-null phenotype and cadherin 1 are known risk factors for gastric cancer and contribute to 1–3% of all gastric cancers." (PMID 34442208, 2021). "Patients with mutations in both GSTT1 and GSTM1 had a significantly increased risk of gastric cancer over those with both wild type genotypes (OR = 1.95, 95% CI: 1.42–2.67; I2 = 0%)." (PMID 32899442, 2020). "A case-control study separately associated GSTT1- and GSTM1-null genotypes with increased gastric cancer risk." (PMID 27588484, 2016). "Future studies with large and carefully design are warranted to better understand such a association between GSTM1 null genotype and gastric cancer risk." (PMID 25477765, 2014). "For Caucasians, what is notable that the association between GSTM1 null status and gastric cancer risk simply reaches a slightly statistically significant level." (PMID 25477765, 2014). "It was found that the null genotype of GSTM1 was associated with an increased gastric cancer risk (OR = 1.207, 95% CI: 1.106-1.317, P < 0.001), under the random-effects model (I2 : 49.9%, PQ <0.001)." (PMID 25477765, 2014). "To obtain more precise estimate for the association between GSTM1 polymorphism and gastric cancer risk, we conducted a quantitative meta-analysis of all available studies published until August 15, 2014." (PMID 25477765, 2014). "There was an interaction that only observed for individuals with combined deletion mutations of GSTT1 and GSTM1 genes for gastric cancer risk (OR = 1.505, 95% CI: 1.165-1.944, P = 002)." (PMID 25477765, 2014). "The results of pooling all studies showed that the null genotype of GSTM1 was associated with an increased gastric cancer risk (OR = 1.207, 95% CI: 1.106-1.317, P < 0.001), using the random-effects model (I2 : 49.9%, PQ < 0.001)." (PMID 25477765, 2014). "The present and null genotype of GSTM1 is one of the most widely studied metabolic gene polymorphisms as susceptibility factor for gastric cancer." (PMID 25477765, 2014). "The main finding of this meta-analysis of 54 studies involving 9,322 cases and 15,118 controls is that individuals of GSTM1 null genotype appear to have a significant increased risk of gastric cancer." (PMID 25477765, 2014). "Further investigations on the effect of the interactions of GSTM1 null genotpe and alcohol drinking on gastric cancer risk are required to address this controversy." (PMID 25477765, 2014). "HP infection is a well known risk factor of gastric cancer and 4 studies provided data about HP infection status and GSTM1 genotype distribution." (PMID 24244742, 2013). "Most eligible studies about GSTM1 polymorphism and gastric cancer were small-sized (less than 500 participants)." (PMID 24244742, 2013). "By pooling all 46 eligible studies, we found the GSTM1 null genotype was associated with a significantly increased risk of gastric cancer (OR=1.217, 95% CI: 1.113-1.331, Pheterogeneity<0.001)." (PMID 24244742, 2013). "Since a large number of studies have been published, it is necessary to perform an update meta-analysis to assess the association between GSTM1 and gastric cancer and explore the effect of H. pylori infection, smoking, location and Lauren’s classification." (PMID 24244742, 2013). "In recent years, several common low-penetrant genes have been identified as potential gastric cancer susceptibility genetic variants, such as Glutathione S-transferase M1 (GSTM1) polymorphism." (PMID 24069142, 2013). "A lot of epidemiological studies have investigated the association of GSTM1 depletion with risk of gastric cancer and several meta-analyses have been performed to clarify this issue." (PMID 24244742, 2013).
gastric cancer (continued). "The null genotype of GSTM1 causes total loss of GSTM1 enzyme activity and numerous studies have investigated the association between GSTM1 null genotype and gastric cancer risk." (PMID 24244742, 2013). "Pooled results showed that the GSTM1 null genotype was associated with a significantly increased risk of gastric cancer (OR=1.217, 95% CI: 1.113-1.331, Pheterogeneity<0.001)." (PMID 24244742, 2013). "This meta-analysis was designed to investigate the relationship between GSTM1 null genotype and susceptibility to gastric cancer and assess the influence of Helicobacter pylori infection, smoking, Lauren’s classification, and other factors." (PMID 24244742, 2013). "For example, two meta-analyses that explored the relevance of GSTM1 null status on stomach cancer found a modest risk increase." (PMID 19755987, 2009). "The first meta-analysis evaluating the association between GSTM1 status and gastric cancer included 15 primary studies in English language and was published in 2005." (PMID 19506726, 2008). "Saadat described an additive effect for GSTT1 and GSTM1 genotypes, taking into account the effects of each of the functional polymorphisms on gastric cancer risk." (PMID 19506726, 2008). "Polymorphisms of GSTM1 have also been shown to increase gastric cancer risk." (PMID 32899442, 2020). "The GSTM1 null genotype was associated with higher risk for colorectal and gastric cancers." (PMID 27588484, 2016). "For Negroids, it might seems that the low prevalence of this viriant and the low number of samples would make it difficult to detect an association between GSTM1 null phenotype and gastric cancer risk with only 13 cases and 15 controls." (PMID 25477765, 2014). "Furthermore, we carried out the subgroup analysis on alcohol drinking to detect the possible effect of GSTM1 deficiency on gastric cancer risk." (PMID 25477765, 2014). "However, a review of genetic susceptibility and gastric cancer risk reported that the results of case–control studies detailing associations between the GSTM1 gene and gastric cancer risk are controversial." (PMID 25477765, 2014). "This meta-analysis suggests that the null genotype of GSTM1 are associated with increased gastric cancer risk, and the subgroup meta-analysis on the basis of ethnicity showed that significant associations are found for Asians and Caucasians, but not for Negroids." (PMID 25477765, 2014). "Thus, in our meta-analysis we initially included a total of 54 studies which assessed the associations between GSTM1 polymorphism and gastric cancer." (PMID 25477765, 2014). "Hence, to derive the most comprehensive assessment of the associations between the GSTM1 polymorphism and gastric cancer risk, we undertook an updated meta-analysis of all available studies." (PMID 25477765, 2014). "This shows that the null genotype of GSTM1 might increase gastric cancer risk associated with the GSTT1 null genotype." (PMID 25477765, 2014). "There were 14 studies focused on the joint effect of GSTM1 null genotype and smoking status on gastric cancer risk, four investigated the joint effect of GSTM1 null genotype and alcohol drinking, and seven eveluated the joint effect of GSTM1 null genotype and Helicobacter pylori infection." (PMID 25477765, 2014). "This meta-analysis suggests that the null genotype of GSTM1 may be a important genetic risk factor for gastric cancer development." (PMID 25477765, 2014). "Hence, we also investigate the possible interaction between GSTT1 and GSTM1 status and gastric cancer risk in this meta-analysis." (PMID 25477765, 2014). "Therefore, the effect of the interactions between GSTM1 polymorphism and alcohol drinking on gastric cancer risk should be noted." (PMID 25477765, 2014).
gastric cancer (continued). "Since the first study in 1991 by Strange and colleagues which reported the association between the GSTM1 null genotype and increased risk of gastric cancer, a lot of epidemiological studies about the relationship between GSTM1 and gastric cancer have been conducted." (PMID 24244742, 2013). "Considering that the GSTM1 null genotype caused a complete loss of GSTM1 enzyme activity, it is biologically plausible that the GSTM1 null genotype may increase risk of gastric cancer." (PMID 24244742, 2013). "Meta-analysis results of GSTM1 polymorphism and gastric cancer risk." (PMID 24244742, 2013). "In numerous studies the GSTM1, GSTT1, and GSTP1 gene polymorphisms have been investigated for their possible role in risk occurrence of various diseases, including gastric cancer." (PMID 28182092, 2017). "The most commonly deleted polymorphisms in the GSTT1 and GSTM1 genes associated with decreased detoxifying activity of the GST enzyme were extensively studied for gastric cancer occurrence and less frequently for premalignant lesions." (PMID 28182092, 2017). "Many studies showed that the polymorphic variants of GSTT1, GSTM1, and GSTP1 genes were associated with increased risk for gastric cancer, especially in the Asian population." (PMID 28182092, 2017). "Limited by number of studies, the conclusion about GSTM1 null genotype and gastric cancer was still unclear, as well as influence of some important factors like H. pylori infection and smoking status." (PMID 24244742, 2013). "It has also been shown that the GSTM1 positive genotype evidenced a significantly better time to progression in cases of advanced gastric cancer being treated with FOLFOX." (PMID 23876227, 2013). "In gastric cancer, GSTM1-wt patients show better tumor-related and disease-free survival." (PMID 32539715, 2020). "Carriers of the double-null genotype, lacking both GSTT1 and GSTM1, display increased gastric cancer risk relative to non-carriers in an Italian population and by a meta-analysis." (PMID 27588484, 2016). "For the subgroup meta-analyses of ethnicity, which categorized as Asians, Caucasians and Negroids, the results showed that the GSTM1 null phenotype predisposes to gastric cancer in both Asian and Caucasian populations, but not in Negroids." (PMID 25477765, 2014). "Both of them found that a excess gastric cancer risk was probably associated with GSTM1 null genotype in Asians, but not in Caucasians." (PMID 25477765, 2014). "For smoking status, the GSTM1 null genotype increased risk of gastric cancer in both ever-smokers and non-smokers." (PMID 24244742, 2013). "In this meta-analysis based on 46 epidemiological studies, we show that the GSTM1 null genotype is associated with an increased risk of gastric cancer among Asians but not among Caucasians." (PMID 24244742, 2013). "To summary, in this meta-analysis based on 46 epidemiological studies, we show that the GSTM1 null genotype is associated with increased risk of gastric cancer among Asians but not among Caucasians." (PMID 24244742, 2013). "To assess the influence of smoking, we extracted data from 12 eligible studies and found that smoking status did not alter the relationship between GSTM1 null genotype and risk of gastric cancer." (PMID 24244742, 2013). "We also undertook gene-gene interaction analysis between GSTM1 and GSTT1 genes for gastric cancer risk, and the results indicated that the dual null genotypes of GSTM1 and GSTT1 might elevate the risk of gastric cancer (OR = 1.505, 95% CI: 1.165-1.944, P = 002)." (PMID 25477765, 2014). "In additon, the null genotype of GSTM1 may modulate the smoking-related and Helicobacter pylori-related carcinogenesis of gastric cancer, and that the combination of unfavourable GSTT1 polymorphism may result in an additional risk of gastric cancer." (PMID 25477765, 2014).
gastric cancer (continued). "The identified synergistic interaction among GSTs null genotypes as well as the relationship between GSTM1 and CYP2E1 unfavourable variants suggest that a wide portion of gastric cancer could be attributable to the inheritance of both unfavourable polymorphisms." (PMID 19506726, 2008). "Four distributed genes ACOT1, GSTM1, SIGLEC14, and UGT2B17 showed extremely high frequencies of absence in the gastric cancer population." (PMID 36109518, 2022). "Genes ACOT1, GSTM1, SIGLEC14, and UGT2B17 are highly absent in Chinese Hans, even in the Asian population, compared to the non-Asian healthy population, suggesting a potential association for the high incidence of gastric cancer in the Asian population." (PMID 36109518, 2022). "Genes ACOT1, GSTM1, SIGLEC14 and UGT2B17 are identified as highly absent genes in gastric cancer population." (PMID 36109518, 2022).